RAE1 (ribonucleic acid export 1)
Diseases named in the same sentence as RAE1 in open-access papers (continued):
Sharing a sentence is not in itself a finding about the gene and the disease.
COVID-19 (2 papers, 2021). A disease caused by infection with severe acute respiratory syndrome coronavirus 2. "After the outbreak of COVID-19 caused by SARS-CoV-2, Gordon and colleagues revealed a convincing interplay between SARS-CoV-2 Orf6 and the host Rae1–Nup98 complex which is responsible for nucleocytoplasmic shuttling of mRNA." (PMID 35096974, 2021).
diabetes (2 papers, 2017 to 2018). "In a previous study with the NOD mouse model, expression of RAE1 was observed in the pancreatic islets, and Ab blockade of NKG2D was found to inhibit CD8+ T cell infiltration and prevent diabetes development." (PMID 29497709, 2017). "Although transgenic expression of RAE1 led to spontaneous insulitis in old Rae1-Tg mice, no diabetes development could be observed in this model." (PMID 29910814, 2018).
influenza (2 papers, 2019 to 2020). An acute viral infection of the respiratory tract, occurring in isolated cases, in epidemics, or in pandemics; it is caused by serologically different strains of viruses (influenzaviruses) designated A, B, and C, has a 3-day incubation period, and usually lasts for 3 to 10 days. "Influenza infection also leads to the expression of inducible stress proteins such as H60, Rae-1, and Mult1 in infected cells that are the cognate ligands for the activation receptor NKG2D46." (PMID 30899058, 2019).
liver cancer (2 papers, 2013 to 2017). An epithelial or non-epithelial malignant neoplasm that arises from the liver. "The mRNA and protein expression levels of GM-CSF, IL-21 and Rae-1 in spleen tissues decreased compared with the corresponding expression in liver cancer tissue in the Bio-CS/plasmid DNA and plasmid DNA groups (P < 0.01)." (PMID 28938619, 2017). "In summary, GM-SCF, IL-21 and Rae-1 greatly inhibited the growth of liver cancer in a relevant mouse model." (PMID 24350772, 2013). "Meanwhile, in tumor cells that are recognized by CTL and NK cells (e.g., MHC-1 ligand and Rae-1) obviously decrease or disappear, and liver cancer cells survive in the host." (PMID 24350772, 2013). "The recombinant expression plasmid inhibited liver cancer by a mechanism that involved activation of cell-mediated immunity and Rae-1 in liver cancer." (PMID 24350772, 2013). "RT-PCR and Western blot assays were used to detect liver cancer tissues and to analyze the effect of GFP, GM-SCF, IL-21 and Rae-1 constructs and protein expression in liver cancer tissue." (PMID 24350772, 2013). "Most NK and CTL cells express the Rae-1 receptor, which easily combines with Rae-1 that is expressed by liver cancer tissues to enhance the removal of cancer tissue by NK cells and CTL." (PMID 24350772, 2013). "We also found that the survival rates of mice were highest in the IRES/combination group, which indicated that recombinant genes of GM-SCF, IL-21, and Rae-1 displayed the most effective treatment against liver cancer." (PMID 24350772, 2013). "Liver cancer specimens were isolated for Rae-1 expression by RT-PCR and Western blot, and splenocytes were analyzed by flow cytometry." (PMID 24350772, 2013). "The recombinant expression plasmid also augmented Rae-1 expression by liver cancer cells." (PMID 24350772, 2013). "Therefore, in this study, the combination of GM-SCF, IL-21 and Rae-1 collectively activated the murine immune system in liver cancer, and increased the numbers and cytotoxic activities of NK and CTL cells." (PMID 24350772, 2013). "A recombinant plasmid capable of co-expressing granulocyte-macrophage colony- stimulating factor (GM-SCF), interleukin-21 (IL-21), and retinoic acid early transcription factor-1 (Rae-1) was constructed, and its effects determined in a mouse model of subcutaneous liver cancer." (PMID 24350772, 2013). "Our study showed that pGM-CSF-IL-21-Rae-1 increased the number and cytotoxicity of CTL and NK cells, and enhanced the expression of Rae-1 in liver cancer tissues." (PMID 24350772, 2013). "In this study, we treated liver cancer with a recombinant plasmid of GM-SCF, IL-21 and Rae-1 and found that the frequency of Tregs was significantly decreased as compared with treatment using a single gene." (PMID 24350772, 2013).
sarcoma (2 papers, 2013 to 2020). A usually aggressive malignant neoplasm of the soft tissue or bone. "Although NKG2D ligand expression is variable and often not detectable on sarcomas originating in wild type (WT) mice, sarcomas derived from perforin-deficient mice were RAE-1+ and immunogenic when transferred into WT syngeneic mice." (PMID 33322371, 2020).
T cell lymphoma (2 papers, 2010 to 2016). "YAC-1 T cell lymphoma cells expressed Rae-1, H60 and MULT1 messages and surface proteins, whereas RMA T cell lymphoma cells did not express Rae-1, H60, only low levels of MULT1 mRNA, and none of these surface proteins, and served as negative controls." (PMID 20523894, 2010).
adenoma (1 paper, 2017). A neoplasm arising from the epithelium. "Myc rapidly induced expression of Rae-1, the principal activating ligands for the NK cell NKG2D receptor, in adenoma epithelial cells." (PMID 29195074, 2017).
Autoimmunity (1 paper, 2017). The occurrence of an immune reaction against the organism's own cells or tissues. "Hence, MICA expression is prone to a rapid recognition by NKG2D-bearing IELs, while ULBP1–3 and murine RAE-1 become available only in the event of epithelial polarity breaking, as result of infection or autoimmunity." (PMID 29209320, 2017).
chronic obstructive pulmonary disease (1 paper, 2020). A chronic and progressive lung disorder characterized by the loss of elasticity of the bronchial tree and the air sacs, destruction of the air sacs wall, thickening of the bronchial wall, and mucous accumulation in the bronchial tree. "An example of this is the aberrant expression of RAE1 in pulmonary epithelial cells, which has previously been shown to contribute to chronic obstructive pulmonary disease (COPD) via cytotoxic lymphocytes in an NK but not T-cell dependent manner." (PMID 32153361, 2020).
colon cancer (1 paper, 2022). "The transcript levels of four NUPs (NUP210, NUP58, NUP37, and Rae1) were higher in colon cancer tissue among BRD4-bound NUPs." (PMID 35159127, 2022).
colorectal cancer (1 paper, 2022). A primary or metastatic malignant neoplasm that affects the colon or rectum. "The high expression level of RAE1 was reported as an independent poor prognostic factor for colorectal cancer." (PMID 35751040, 2022).
colorectal tumor (1 paper, 2022). "RAE1 also promoted colorectal tumor growth through inhibiting apoptosis and promoting cell cycle progression in part by stabilization of spindle bipolarity." (PMID 35751040, 2022).
gastric cancer (1 paper, 2022). A primary or metastatic malignant neoplasm involving the stomach. "Furthermore, three genes that we found to be amplified in serum-treated HEK293T cells (i.e., AURKA, RAE1, and ZFP64) are known to increase the resistance of pancreatic, colorectal, and gastric cancer cells to paclitaxel." (PMID 36289850, 2022).
Hepatitis (1 paper, 2018). Inflammation of the liver. "Although our results show the involvement of NKG2D in the development of Con A-induced hepatitis, the participation of NKG2D/RAE-1 (and other ligands) appeared to be partial and the survival was not equivalent to that of NKT cell-deficiency." (PMID 29868013, 2018).
invasive ductal carcinomas (1 paper, 2017). "A combined tissue microarray (TMA) and survival analysis revealed the prognostic significance of RAE1 and a positive correlation between RAE1 expression and histologic grade in invasive ductal carcinomas." (PMID 28181567, 2017).
lung adenoma (1 paper, 2017). A benign, well circumscribed epithelial neoplasm that arises from the bronchus or the lung parenchyma. "This rapid expulsion of NK cells is especially intriguing given that Myc activation also triggered a profound upregulation of Rae-1 NKG2D ligands and downregulation of major histocompatibility complex (MHC) class I —both potent activating signals for NK-like cells —in lung adenoma cells." (PMID 29195074, 2017).
lung carcinoma (1 paper, 2012). "A prognostic score based on the expression of ADAR2 and four additional RNA metabolism-related genes (MARS, RAE1, SNRPB and SNRPE) can stratify lung cancer patients into high and low risk groups for cancer death." (PMID 22876301, 2012).
Obesity (1 paper, 2014). Accumulation of substantial excess body fat. "The mRNA levels of Rae-1 and Mult-1 were highest at the earliest time-point measured (3 weeks post-initiation of diet) and gradually decreased during the progression of obesity." (PMID 25333972, 2014).
osteosarcoma (1 paper, 2022). A usually aggressive malignant bone-forming mesenchymal neoplasm, predominantly affecting adolescents and young adults. "The critical value of USP11 in the occurrence and progression of osteosarcoma has been identified via its deubiquitylation and stabilization of RAE1." (PMID 35715413, 2022).
ovarian tumor (1 paper, 2013). "We showed that ovarian tumor cells that express the NKG2D ligand Rae-1 can be bound by the chimeric NKG2D-Fc-RO protein and present the OVA CTL peptide through MHC class I molecules." (PMID 24354786, 2013). "Both NKG2D-Fc-RO and NKG2D-Fc bound to the NKG2D ligand-expressing murine ovarian tumor cells, MOVCAR, but not to the Rae-1-negative B16F10 tumor cells." (PMID 24354786, 2013). "To determine if the purified NKG2D-Fc-RO protein could bind to murine NKG2D ligand-expressing tumor cells, we selected a Rae-1 (a murine NKG2D ligand)-expressing ovarian tumor cell line (MOVCAR) and one Rae-1-negative tumor cell line (B16F10) for our studies." (PMID 24354786, 2013).
salivary gland tumors (1 paper, 2010). "We established several cell lines from salivary gland tumors isolated from PyV-infected TCRβ×δ KO mice and tested them for the expression of the NKG2D ligands Rae-1, H60 and MULT1." (PMID 20523894, 2010).
thyroid carcinoma (1 paper, 2022). "However, RAE1 expression level was significantly downregulated in tissues of kidney renal clear cell carcinoma (KIRC) and thyroid carcinoma (THCA)." (PMID 35751040, 2022).
tumor (73 papers, 2007 to 2025). "In contrast, messenger substances such as retinoic acid early-inducible gene (RAE-1)-encoded proteins, which are expressed on the surface of pathogenic virus-infected or tumor cells, serve as activation signals for NK." (PMID 39941044, 2025). "MT-RNR2-Like 3 and 6 (MTRNR2L3/6) and Ribonucleic Acid Export 1 (RAE1), which are less well-defined in the context of BC but generally linked to tumor aggressiveness, were also upregulated in 7 %1g compared to control 1g but downregulated in the 0g conditions." (PMID 40124331, 2025). "They further found that ribonucleic acid export 1 (RAE1)-high tumor cells were destroyed and the cells with RAE1 loss/low expression still survived." (PMID 32571374, 2020). "Along with our previous study describing RAE-1 molecules expressed on tumor-associated endothelium, these datasets represent a substantial addition to our understanding of NKG2D ligand expression on tumor-associated cells in multiple tumor models." (PMID 29757143, 2018). "Our study showed that levels of both INF-γ and IL-2 in mice treated with recombinant GM-CSF, IL-21 and Rae-1 gene expression vectors were highly expressed and negatively associated with the tumor volumes seen in tumor-bearing mice." (PMID 24350772, 2013). "For example, experimentally induced tumour cells were positive for RAE-1 protein expression in perforin-deficient mice, whereas expression was low or absent in WT mice, indicating a selection pressure exerted by the immune system for cancer cells to reduce or lose expression of NKG2DLs." (PMID 33352921, 2020). "Nonetheless, most activated cytotoxic CD8+ T cells (human and mouse) share the expression of the natural killer group 2, member D receptor (NKG2D) encoded by Klrk1, which upon binding to RAE-1 or related ligands, induced on tumor cells, stimulates effector responses that are independent of TCR21." (PMID 28220815, 2017). "Furthermore, RAE1 overexpression was associated with considerably poorer disease-free survival and distant metastasis-free survival, especially in patients with oestrogen receptor-positive tumours." (PMID 28181567, 2017). "This enabled us to identify the core genes associated with tumor stemness induced by tumor intrinsic variations and finally we selected four genes: RAD21, EXOSC4, CSE1L and RAE1." (PMID 40406120, 2025). "We detected an effect on the expression of RAE-1 upon treatment in vitro as well as in vivo, it is therefore likely that Sulanemadlin is capable of reaching the tumor efficiently." (PMID 38784022, 2024). "Both monotreatment with Sulanemadlin and the combination treatment, Sulanemadlin + anti-PD-1 immunotherapy led to a significantly higher number of RAE-1 positive cells/mg tumor as well as a significantly higher number of NK cells/mg tumor." (PMID 38784022, 2024). "We conclude that Sulanemadlin treatment increases the protein expression of MHC I and RAE-1, proteins important for immune cell detection of tumor cells." (PMID 38784022, 2024). "When we analyzed the expression of RAE-1 in the CD45−tumor cells we noticed that the tumor size/weight correlated with RAE-1 protein expression, with a higher number of cells per mg of tumor expressing this marker the smaller the tumor was." (PMID 38784022, 2024). "For example, tumor-experienced NK cells have been shown to take-up tumor-derived Rae-1, a ligand for NKG2D, resulting in their detection and killing by other tumor-naïve NK cells via the NKG2D-induced perforin pathway." (PMID 37974170, 2023). "We used the A20 cell line as a tumor target because we previously showed that A20 cell line express NKG2D ligands including Rae1, H60, and MULT1." (PMID 36562825, 2023). "In our results, exercise training increased the expression of NK cell ligands Nkg2d and Rae-1 in liver tissue of tumor-bearing mice, and the content of IFN-γ was increased." (PMID 37585912, 2023).
tumor (continued). "Univariate Cox regression analysis indicated that T stage, M stage, pathologic stage, tumor status, and RAE1 expression level were significantly correlated with a poor OS." (PMID 35751040, 2022). "The expression level of RAE1 showed the ability to accurately distinguish tumor tissues from normal tissues (area under the curve (AUC) = 0.951)." (PMID 35751040, 2022). "HCC patients with a higher expression level of RAE1 had a poorer prognosis, and the expression level of RAE1 showed the ability to accurately distinguish tumor tissues from normal tissues (area under the curve (AUC) = 0.951)." (PMID 35751040, 2022). "An elevated RAE1 expression level was correlated with a higher T stage, pathologic stage, tumor status, histologic grade, and AFP level." (PMID 35751040, 2022). "The high expression level of RAE1 was correlated with T stage, pathologic stage, tumor status, histologic grade, and alpha-fetoprotein level." (PMID 35751040, 2022). "The high expression level of RAE1 was significantly correlated with T stage (P < 0.001), pathologic stage (P < 0.001), tumor status (P = 0.012), histologic grade (P < 0.001), and alpha-fetoprotein (AFP) level (P < 0.001)." (PMID 35751040, 2022). "MICA and MICB (Rae1 in mouse) have a key role in the recognition of tumor cells by the innate immune system where their engagement with NKG2D receptors on NK cells triggers NK cell-mediated cytotoxicity." (PMID 33789714, 2021). "IRF3 activation in response to DDR promotes its role in upregulating RAE1, which is the tumor-cell ligand for NKG2D on NK cells." (PMID 34488791, 2021). "Various studies revealed tumour cells induced to express RAE-1 and H60 proteins resulted in tumour rejection in mice in an NK cell-dependent manner." (PMID 33352921, 2020). "NKG2D ligands such as RAE1 can be expressed by proliferating tumor cells or at times of cell stress such as during DNA damage or tissue injury." (PMID 30712871, 2019). "In tumor-bearing mice, Rae-1 was detected on a subset of MDSCs and contributed to NK cell activation." (PMID 29740438, 2018). "Collectively, data here and in previous studies revealed multiple roles of RAE-1 molecules on macrophages, tumor cells, endothelial and other cells." (PMID 29757143, 2018). "Accordingly, Rae-1 expression on lymph node endothelial cells in steady state or by myeloid cells in tumor-bearing animals is responsible for NKG2D downregulaton and global desensitization of NK cells." (PMID 29740438, 2018). "QBKPN administration resulted in an increase in NKG2D ligand (RAE1) positive immune cells and cancer cells in mouse lungs, suggesting an increased stress response in the tumor." (PMID 29399400, 2018). "Immunohistochemistry on liver and tumour sections detected the presence of RAE-1 on the cell surface of transformed hepatocytes as well as on normal hepatocytes of the surrounding area." (PMID 28128200, 2017). "By contrast, tumors excised from wt or Cbx3/HP1γ-insufficient mice expressed similar levels of the stimulatory RAE-1 and inhibitory programmed cell death ligand 1 (PD-L1) ligands, both of which were induced in tumor cells." (PMID 28220815, 2017). "As to the underlined mechanisms on the early formation or rejection of the allogeneic tumors in mice, we found that the expressed NKG2DL on tumor cells, especially RAE-1, was one of the determining factors." (PMID 27448968, 2016). "The tumor-protective mechanism involves signaling between Rae-1 expressing keratinocytes and the natural killer group 2D receptor on immune cells, which also plays a role in host defenses against infection." (PMID 26763429, 2016). "We used Rae-1–overexpressing CT26 tumor cells to generate 60 hybridomas that secreted mAbs against Rae-1." (PMID 24495546, 2014). "The current study focuses on stimulating either cell-mediated immune activation including CTL and NK cells, or enhancing the expression of molecules like Rae-1 that are expressed by tumor cells and subsequently identified by host immunity." (PMID 24350772, 2013).